ALB (albumin)
Diseases named in the same sentence as ALB in open-access papers (continued):
Sharing a sentence is not in itself a finding about the gene and the disease.
depression (continued). "This study aims to explore the correlation between the red blood cell distribution width (RDW) to albumin ratio (RAR), a practical measure for assessing inflammation, and depression in the general population." (PMID 39950171, 2025). "In the next step, the concentrations of zinc, albumin a, CRP, and IL-6 were compared between the groups of patients with unipolar depression (UD), bipolar depression (BDD), and the group of healthy subjects (HC)." (PMID 38785543, 2024). "Our study, together with previous ones, have effectively illustrated that albumin may play a role as a clinical immunoinflammatory predictor in depressive symptoms and the depressive symptoms of other somatic diseases, providing some clues to the mechanisms of depression." (PMID 37340352, 2023). "Multivariable logistic regression analysis showed that WMH at the GCC, depression, NIHSS score, and albumin at admission were important determinants of long-term cognitive impairment after ALS." (PMID 37881309, 2023). "Serum albumin is the main extracellular molecule responsible for maintaining the plasma redox status, and reduced albumin may lead to oxidative stress dysregulation, while higher free-radical and oxidative damage levels are detectable in patients with depression." (PMID 37340352, 2023). "Multivariable logistic regression analysis showed that depression (OR = 6.252, P = 0.029), NIHSS score (OR = 1.24, P = 0.011), and albumin at admission (OR = 0.841, P = 0.032) were also important determinants of long-term cognitive impairment after ALS." (PMID 37881309, 2023). "Comparison with the BD depressive episodes group showed that the platelet counts, MPV, PCT, neutrophil counts, SII and PAR values were elevated (P < 0.05), and the albumin levels and RPR values were decreased (P < 0.05) in the BD manic episodes group." (PMID 35216557, 2022). "Clinical depression is accompanied by increased O&NS and impaired antioxidant status (e.g., lower TRP, tyrosine, albumin, zinc)." (PMID 33255237, 2020). "Patients’ depression was assessed using Beck depression inventory second edition (BDI-II) biochemical parameters (hemoglobin, serum albumin, etc) and CRP levels were measured at baseline and at weeks 4, 8 and 12 of the study." (PMID 28487875, 2017). "The serum antioxidant levels are significantly lower in depression in our study and previous reports, including PON, albumin, zinc, uric acid HDL-C, CoQ10 and GSH." (PMID 26445247, 2015). "Feature selection identified 13 predictive variables: age, operation time, length of hospital stay, pain score, white blood cell count, albumin, C-reactive protein, CA125, education level, history of depression/anxiety, postoperative insomnia, fatigue, and opioid analgesic use." (PMID 42023444, 2026). "Research from Jordan and America has indicated a negative correlation between serum albumin and depression." (PMID 40182647, 2025). "In summary, although the exact mechanisms remain to be fully elucidated, the evidence suggests that serum albumin and monocyte counts may have different effects on the relationship between the PINI and mortality in individuals with depression." (PMID 40718002, 2025). "L demonstrated a negative correlation with obsessive-compulsive symptoms, depression, and anxiety, while exhibiting a positive correlation with serum albumin levels." (PMID 40963810, 2025). "Multivariable logistic regression, restricted cubic splines (RCS), sensitivity analyses with alternative depression definitions, E-value analysis, and ROC curve comparisons with the RDW-to-albumin ratio (RAR) were conducted, adjusted for sociodemographic, lifestyle, and clinical confounders." (PMID 41036125, 2025). "And it is worth noting that there is currently no systematic study comparing the association and potential differences between serum globulin levels, albumin-globulin ratios and depression between cancer and non-cancer populations." (PMID 40276074, 2025).
depression (continued). "Patients with depression often exhibit dysregulated levels of inflammatory markers; for instance, those with metastatic lung cancer combined with depression may have elevated C-reactive protein (CRP) levels and an increased CRP/albumin ratio." (PMID 40110200, 2025). "The neutrophil percentage-to-albumin ratio (NPAR) is an emerging inflammatory marker, but its association with depression in middle-aged and elderly adults was not previously explored." (PMID 40182647, 2025). "ALB and HGB levels partially mediate the association between nocturia, depression, and CI in older adults." (PMID 40672414, 2025). "Combining KXS drastically ameliorated the Hamilton Depression 17 (HAM-D17) rating scores and self-rating depression scale scores, and the serum lipoprotein B, apolipoprotein C3 and albumin levels and low-density lipoprotein cholesterol/high-density lipoprotein cholesterol ratio." (PMID 38362144, 2024). "Thus, depression (OR = 6.252, P = 0.029), NIHSS score (OR = 1.24, P = 0.011), albumin level (OR = 0.841, P = 0.032), WMH at the GCC (OR = 3.1, P = 0.033), and frontal WMH volume (OR = 1.18, P = 0.04) were used to construct a cognitive prediction scale." (PMID 37881309, 2023). "Many studies have found that lower serum albumin levels are related to depression in distinct groups of psychiatric and non-psychiatric patients." (PMID 35457752, 2022). "In the present study, the most promising biomarkers of neuroinflammation related to depression will be investigated including total CSF WCC, CSF/serum albumin ratio, CSF total protein, IgG index, CSF levels of IL-6 and IL-8, and any CNS-reactive autoantibody in CSF and/or blood." (PMID 35022028, 2022). "First, depression is accompanied by lowered levels of albumin, a negative APP, whilst a large part of the TRP pool is bound to albumin in the peripheral circulation." (PMID 36231075, 2022). "To date, however, no study has examined the relationship between serum albumin level and depression in CLD patients." (PMID 34983435, 2022). "Compared with the healthy control group, the levels of SBP, DBP, TG, Cr, BUN, K+, phosphate and depression scores of the ESRD patients without depression were significantly increased, while HB and albumin were significantly decreased." (PMID 34723750, 2021). "As the stage of depression increased, the degree of current disease activity DAS28-CRP, patient overall disease-VAS was significantly increased, whereas age, disease duration and laboratory data including hemoglobin, albumin and CRP were unchanged." (PMID 34351967, 2021). "The overlap between the two groups was a decrease in serum total protein and albumin in patients with anxiety and depression, and this difference was more pronounced among depressed/nondepressed patients." (PMID 34007268, 2021). "Furthermore, lower serum levels of albumin and high-density lipoprotein cholesterol (HDL-C) have been observed in patients with depression compared to healthy controls." (PMID 32658906, 2020). "Serum concentrations of 25(OH)D, albumin, hemoglobin and BMI were significantly lower in participants with depression than those without (Ps < 0.01)." (PMID 30157761, 2018). "Insulin resistance indices in the depression group (HOMA-IR: 3.05 vs. 2.49; LAP: 48.79 vs. 38.49; TyG: 8.71 vs. 8.55) and inflammatory markers (white blood cell count, neutrophil count, platelet count) were significantly elevated, while serum albumin levels were lower." (PMID 40551244, 2025). "Other findings of a case-control study which included sixty-one psychiatric inpatients either with or without suicide attempts showed the means of serum albumin concentration in major depression and mania cases were significantly lower than that of the controls." (PMID 37880606, 2023). "Furthermore, increased IL-6 as well as decreased interleukin-4 (IL-4) and albumin in serum discriminate MS patients with from those without depression." (PMID 34764926, 2021).
depression (continued). "In addition, Charlson Comorbidity Index and serum albumin level were independent predictors of patient survival, but depression was not an independent predictor." (PMID 32758180, 2020). "Whereas hemoglobin, hematocrit and albumin were lower among ESRD patients without major depression." (PMID 28487875, 2017). "However, in the present study, lack of a significant relationship between depression and serum albumin may be due to better nutrition intake in participating hemodialysis patients and higher level of albumin compared to previous studies." (PMID 27045404, 2016). "Depressed patients also had lower levels of hemoglobin and serum albumin, and had higher BUN levels, compared with those without depression." (PMID 36612797, 2022). "Other factors of frailty in elderly patients with hip fractures such as gender, the level of serum albumin (ALB), 25-(OH) VD (25-hydroxy vitamin D), deep vein thrombosis (DVT), handgrip strength, depression, and the mobility before fractures have not yet been synthesized in a meta-analysis." (PMID 40260264, 2025). "The relationship between the albumin-to-globulin ratio (AGR) and depression is not well understood." (PMID 39421614, 2024). "In the BD depressive episodes group, the Spearman correlation analysis revealed that the PLR, SII and RPR had positive correlations with age (P < 0.05), but platelet, MPV, PCT, lymphocyte and albumin values had negative correlations with age (P < 0.05)." (PMID 35216557, 2022). "White blood cell count or albumin level were not significantly different between the two groups (p = 0.2346, 0.0662, respectively), while inflammatory markers including CRP (p = 0.0190) and ESR (p = 0.0245) were higher in CD patients with symptoms of anxiety/depression versus those without." (PMID 33446900, 2021). "Thus, our results do not support the depression-inflammation hypothesis with respect to the biomarkers assessed (CRP, IL-18, IL-1-ra, albumin, fibrinogen)." (PMID 23967272, 2013).
gastric cancer (215 papers, 2008 to 2026). A primary or metastatic malignant neoplasm involving the stomach. "In gastric cancer, a lower albumin/D-dimer ratio (<41.6) has been associated with reduced disease control and poorer survival outcomes." (PMID 40283046, 2025). "Higher levels are linked to low hemoglobin and albumin and elevated C-reactive protein in gastric cancer." (PMID 39859417, 2025). "A previous study found that an albumin level ≤ 35 g/L was associated with a 3.65 months shorter survival in patients diagnosed with gastric cancer, compared to patients with normal albumin values." (PMID 37880704, 2023). "Previous findings have confirmed that serum albumin can be an independent risk factor for the prognosis of several malignancies, including colon cancer, gastric cancer, small-cell lung cancer, and esophageal squamous cell carcinoma." (PMID 37729271, 2023). "In contrast, CRP-spike was associated with lower PS and NLR in the gastric cancer cohort and higher haemoglobin and albumin in the oesophageal cancer cohort." (PMID 39516365, 2023). "The exact mechanism whereby low platelet and albumin levels are associated with precancerous lesions of gastric cancer will also be investigated in future studies." (PMID 36344959, 2022). "The same study found that age, tumor type, lymph node metastasis, and the serum level of albumin are closely associated with the postoperative survival of patients with gastric cancer." (PMID 35758361, 2022). "Reduced serum concentration of albumin was associated with poor prognosis in multiple cancers including non-small cell lung cancer, prostate cancer and gastric cancer." (PMID 35646669, 2022). "Low levels of HGB and ALB were associated with poor prognosis in patients with advanced gastric cancer." (PMID 34895168, 2021). "An evaluation of weaker associations, for example, between albumin levels and gastric cancer risk was precluded due to low case numbers." (PMID 34041866, 2021). "Studies have shown that preoperative serum albumin levels are associated with the prognosis of several cancers, such as colorectal cancer, pancreatic cancer, ovarian cancer, and gastric cancer." (PMID 31781312, 2019). "This current study aimed to investigate potential risk factors including albumin-to-fibrinogen ratio (AFR) for severe postoperative complications (SPCs) in surgical gastric cancer (GC) patients." (PMID 31533682, 2019). "Previous studies have assessed the association between serum albumin and survival in gastric cancer patients." (PMID 28476041, 2017). "Elevated TBIL and albumin levels were associated with tumor progression and acted as protective prognostic factors in both training and validation cohort gastric cancer patients." (PMID 28476041, 2017). "Elevated C-reactive protein/albumin ratio was an independent predictor for postoperative complications following gastrectomy of gastric cancer, and the diagnostic accuracy was higher than C-reactive protein alone." (PMID 29065877, 2017). "Our study found that although BMI, total protein, and albumin were all associated with gastric cancer patient prognosis, FVC was the only independent risk factor for prognosis." (PMID 28423645, 2017). "Several studies demonstrated that low albumin concentrations are significantly associated with poorer survival in patients with gastric cancer." (PMID 22103888, 2011). "Consequently, higher oxidative stress is linked to lower serum albumin levels, which is a prognostic factor for survival in various cancers, including colorectal, pancreatic, and gastric cancers." (PMID 39385181, 2024). "Albumin was associated with decreased survival in gastric cancer patients." (PMID 37770828, 2023). "Therefore, the effects of probiotics on weight loss, serum albumin and serum prealbumin in gastric cancer patients undergoing surgery were analyzed in this study." (PMID 37901305, 2023).
gastric cancer (continued). "Although these serum biochemical parameters are of less diagnostic value in hepatic metastatic cancer, some of them have been demonstrated to be associated with outcomes of gastric cancer and were incorporated into prognostic prediction model, such as alkaline phosphatase, bilirubin, and albumin." (PMID 36057969, 2023). "In addition, as two crucial inflammatory and nutritional markers, elevated plasma fibrinogen and decreased serum pre-albumin levels have been frequently observed in gastric cancer patients and are associated with poor survival 10-15." (PMID 31772657, 2019). "Additionally, decreased levels of albumin, a factor commonly used as an indicator of nutritional status, are associated with worse outcomes in gastric cancer patients." (PMID 28476041, 2017). "The NRI, a quantitative laboratory marker, integrates serum albumin levels and body weight, which reflect the nutritional status and degree of immune suppression in patients with gastric cancer." (PMID 40589635, 2025). "Another study proposed that the ratio of CRP to albumin (CAR) was a beneficial biomarker for prognosis in patients with gastric cancer." (PMID 40428743, 2025). "The SIS, calculated using serum albumin and LMR, has been primarily studied in gastric cancer, where a high SIS is associated with poor survival." (PMID 40870429, 2025). "The combined use of arginine and glutamine in enteral and parenteral nutrition for patients after gastric cancer surgery has led to increased levels of albumin, serum protein, and transferrin, as well as decreased levels of C-reactive protein, C3, and C4." (PMID 39897929, 2025). "It was initially investigated for its preoperative prognostic significance in gastric cancer patients and calculated as 'Hemoglobin (g/dl) x albumin(g/dl) x lymphocyte count (/μl) x platelet count (/μl)." (PMID 40365347, 2025). "Nutritional assessment indices based on serum albumin levels have been shown to correlate with prognosis and postoperative complications in patients with gastric cancer." (PMID 40144575, 2025). "The significance of the C-reactive protein-albumin-lymphocyte index [CALLY index (CI)] as a prognostic factor in gastric cancer remains unexplored." (PMID 40144575, 2025). "Reports on other cancers, such as gastric cancer, have also indicated a correlation between albumin levels and serosal invasion." (PMID 41008815, 2025). "Hemoglobin and albumin levels are frequently reduced in gastric cancer patients, often approaching the lower limit of the reference range, particularly in those with advanced-stage disease." (PMID 40565788, 2025). "In our present study, we investigated the relationship between pathological response and the CRP/albumin and CEA/albumin ratios in patients receiving neoadjuvant therapy for gastric cancer." (PMID 38792528, 2024). "In this study, we determined the effect of the PPS, a new prognostic indicator that uses prealbumin instead of albumin in the mGPS, on OS after gastrectomy in patients with gastric cancer." (PMID 39594844, 2024). "In current clinical research on albumin NPs for anti-tumor purposes, breast, pancreatic, lung, and gastric cancers are the most widely investigated tumors." (PMID 39070787, 2024). "Another novel index, the alkaline phosphatase to albumin ratio, is an independent prognostic factor for gastric cancer, and when combined with cancer staging, it can provide a more accurate assessment of patient prognosis." (PMID 39553069, 2024). "For example, an elevated C-reactive protein/albumin (CRP/albumin) ratio has been traditionally associated with poor outcomes in septic patients, as well as in cases with hepatocellular, esophageal or gastric cancers." (PMID 39061143, 2024). "In recent studies, a new composite index named HALP, calculated as hemoglobin (g/L) × albumin (g/L) × lymphocyte (/L)/platelet (/L), was reported to be related to survival in gastric cancer, colorectal cancer, bladder cancer, and renal cancer patients." (PMID 39062127, 2024).